MROH2B (maestro heat like repeat family member 2B)
Description:
May play a role in the process of sperm capacitation.
Synonyms: SPIF; HEATR7B2; DKFZp781F0822; FLJ40243
Tractability: PROTAC: ubiquitination databases record sites on it.
Gene: Protein-coding gene on chromosome 5 (40,998,017 to 41,071,342, reverse strand). Ensembl gene ENSG00000171495.
Subcellular location: Cytoplasm; Cytoplasmic vesicle, secretory vesicle, acrosome; Cell projection, cilium, flagellum
Subcellular location (Human Protein Atlas): Acrosome; Mid piece; Cytosol
Gene Ontology:
Molecular function: signaling adaptor activity
Biological process: cAMP/PKA signal transduction
Cellular component: acrosomal vesicle; cytoplasm; sperm flagellum; sperm midpiece; motile cilium
Genetic constraint (gnomAD): Loss-of-function variants: 149 observed, 167.31 expected, observed/expected ratio (o/e) 0.89, 90% interval 0.78 to 1.02. The upper end of that interval is the gene's LOEUF score, 1.02, which puts it in group 4 of 6, group 1 being the genes least tolerant of losing a copy. Missense variants: 1,787 observed, 1,683.7 expected, observed/expected ratio (o/e) 1.06, 90% interval 1.02 to 1.1. Synonymous variants: 659 observed, 594.53 expected, observed/expected ratio (o/e) 1.11, 90% interval 1.04 to 1.18.
Homologues: Orthologues: chimpanzee MROH2B (99% identical), macaque MROH2B (96% identical), dog MROH2B (87% identical), rabbit MROH2B (87% identical), pig MROH2B (86% identical), mouse Mroh2b (81% identical), rat Mroh2b (81% identical), guinea pig MROH2B (80% identical). Paralogues in human: MROH2A (29% identical), MROH1 (27% identical), MROH5 (15% identical), MROH7 (13% identical), MROH8 (12% identical), MROH9 (9% identical), MROH6 (8% identical), MRO (6% identical).
Diseases named in the same sentence as MROH2B in open-access papers:
MROH2B is named in the same sentence as 20 diseases in open-access papers, as found by Europe PMC text mining. Sharing a sentence is not in itself a finding about the gene and the disease.
MROH2B shares sentences with these, for which no sentence is quoted: autoimmune hepatitis (3 papers); autoimmune disease (2); preeclampsia (2); Alzheimer disease (1); autoimmune thyroid disease (1); cancer (1); cat-eye syndrome (1); Cognitive impairment (1); Duchenne muscular dystrophy (1); endometriosis (1); experimental autoimmune encephalomyelitis (1); graft versus host disease (1); immune disorders (1); intrauterine growth restriction (1); neurodegenerative disease (1); pregnancy disorder (1); tuberculosis (1); tumor (1); type 1 diabetes mellitus (1); viral infection (1).